RN7SL809P (RNA, 7SL, cytoplasmic 809, pseudogene)
Gene: Miscellaneous RNA gene on chromosome 12 (56,670,450 to 56,670,746, reverse strand). Ensembl gene ENSG00000241217.
Homologues: Orthologues: chimpanzee Metazoa_SRP (98% identical). Paralogues in human: RN7SL2 (75% identical), RN7SL1 (75% identical), RN7SL45P (74% identical), RN7SL543P (74% identical), RN7SL3 (74% identical), RN7SL147P (73% identical), RN7SL444P (73% identical), RN7SL448P (73% identical), RN7SL44P (73% identical), RN7SL230P (72% identical), RN7SL242P (72% identical), RN7SL88P (72% identical), and 705 more.